PLCXD3 (phosphatidylinositol specific phospholipase C X domain containing 3)
Tractability: PROTAC: its protein half-life has been measured.
Gene: Protein-coding gene on chromosome 5 (41,306,952 to 41,510,601, reverse strand). Ensembl gene ENSG00000182836.
Subcellular location: Cytoplasm
Subcellular location (Human Protein Atlas): Golgi apparatus
Gene Ontology:
Molecular function: protein binding; phosphoric diester hydrolase activity
Biological process: lipid metabolic process
Cellular component: cytoplasm; synapse
Genetic constraint (gnomAD): Loss-of-function variants: 19 observed, 26.54 expected, observed/expected ratio (o/e) 0.72, 90% interval 0.5 to 1.05. The upper end of that interval is the gene's LOEUF score, 1.05, which puts it in group 4 of 6, group 1 being the genes least tolerant of losing a copy. Missense variants: 411 observed, 408.1 expected, observed/expected ratio (o/e) 1.01, 90% interval 0.93 to 1.09. Synonymous variants: 174 observed, 143.8 expected, observed/expected ratio (o/e) 1.21, 90% interval 1.07 to 1.37.
Homologues: Orthologues: chimpanzee PLCXD3 (100% identical), guinea pig PLCXD3 (99% identical), rabbit PLCXD3 (99% identical), pig PLCXD3 (99% identical), dog PLCXD3 (98% identical), mouse Plcxd3 (98% identical), rat Plcxd3 (98% identical), tropical clawed frog plcxd3 (88% identical), zebrafish plcxd3 (81% identical), Drosophila melanogaster CG10747 (29% identical), Caenorhabditis elegans F38E9.1 (26% identical). Paralogues in human: PLCXD2 (52% identical), PLCXD1 (31% identical).
Diseases named in the same sentence as PLCXD3 in open-access papers:
PLCXD3 is named in the same sentence as 15 diseases in open-access papers, as found by Europe PMC text mining. Sharing a sentence is not in itself a finding about the gene and the disease. The quoted sentences say what the papers report.
dyslipidemia (2 papers, 2020 to 2023). "Further investigations revealed that PLCXD3 is involved in insulin signaling and glucose sensing, suggesting that PLCXD3 might be regarded as a candidate gene for pre-diabetes and metabolic syndrome." (PMID 32570874, 2020). "These outcomes were consistent with the literature review, which suggested that up-regulated PLCXD3 might contribute to the progression of NAFLD and AS due to its involvement in hyperinsulinemia and dyslipidemia." (PMID 37063958, 2023).
bipolar disorder (1 paper, 2014). A disorder of the brain that causes unusual shifts in mood, energy, activity levels and the ability to carry out day-to-day tasks.
Hyperglycemia (1 paper, 2019). An increased concentration of glucose in the blood. "Finally, to investigate whether the reduced expression of PLCXD3 was due to the exposure of hyperglycemia status, expression of PLCXD3 was measured in INS-1 (832/13) cells cultured for a short term (24 h) at 11.1 mM (control) and 16.7 or 22.2 mM glucose at mRNA and protein levels." (PMID 31781030, 2019). "The PLCXD3 expression level was significantly unchanged at 16.7 mM glucose as compared to control cells, while at 22.2 mM glucose, we observed increased PLCXD3 expression, indicating that the observed reduction of PLCXD3 expression in diabetic islets is not due to short-term hyperglycemia." (PMID 31781030, 2019).
Insulin resistance (1 paper, 2019). Increased resistance towards insulin, that is, diminished effectiveness of insulin in reducing blood glucose levels. "Collectively, these findings might suggest a potential role of PLCXD3 in the development of insulin resistance by diminishing the expression of INSR and GLUT2, thus resulting in β-cell dysfunction." (PMID 31781030, 2019).
prion disease (1 paper, 2016). A transmissible disease that is caused by a protein that is able to induce abnormal folding of normal cellular proteins, leading to characteristic spongiform brain changes, which are associated with neuronal loss without an inflammatory response. "A recent association study identified variants in or near to the PLCXD3 gene locus as strong disease risk factors in multiple human prion diseases." (PMID 27055460, 2016). "We looked to replicate published findings at PLCXD3 in the context of genomic studies of prion disease." (PMID 27055460, 2016). "Polymorphisms of PLCXD3 are unlikely to be risk factors in human prion disease." (PMID 27055460, 2016).
sporadic CJD (1 paper, 2013). "Sanger resequencing of CJD patients across a region of PLCXD3 with known variants confirmed three SNPs associated with variant and sporadic CJD." (PMID 24028506, 2013).
type 2 diabetes (1 paper, 2020). "Herein, we investigated two genetic variants in the PLCXD3 gene in relation to type 2 diabetes (T2D) or metabolic syndrome (MetS) in the Emirati population." (PMID 32570874, 2020).
metabolic disease (1 paper, 2024). A congenital disorder (due to inherited enzyme abnormality) or acquired (due to failure of a metabolically important organ) disorder resulting from an abnormal metabolic process. "PLCXD3 expression has an important role in glucose sensing and insulin signaling in pancreatic islet β-cells, and its gene knockdown resulted in a significant decrease in insulin secretion, suggesting a possible association between this gene and metabolic diseases." (PMID 39682314, 2024).
neurodegenerative disease (1 paper, 2013). A disorder of the central nervous system characterized by gradual and progressive loss of neural tissue and neurologic function. "The role of PLCXD3 in neurodegenerative disease is as yet unknown, although PI-PLC and specifically Ca2+ homeostasis have been associated with neurodegeneration." (PMID 24028506, 2013).
PLCXD3 also shares sentences with these, for which no sentence is quoted: Creutzfeldt-Jakob disease (1 paper); diabetes (1); gastric cancer (1); Hyperinsulinemia (1); major depressive disorder (1); ovarian carcinoma (1).